SPON2 (spondin 2)
Diseases named in the same sentence as SPON2 in open-access papers (continued):
Sharing a sentence is not in itself a finding about the gene and the disease.
monocytic leukemia (1 paper, 2025). "Previous studies have shown that SPON2 can enhance the secretion of these cytokines, thereby facilitating the polarization of human monocytic leukemia cells (THP-1) toward an M2 phenotype." (PMID 40730813, 2025).
Myocardial fibrosis (1 paper, 2024). "Similar to SPON2 and THBS2, in pre-clinical models, myocardial MFAP4 expression appears to protect from myocardial fibrosis and hypertrophy in response to pressure overload or neurohormonal activation." (PMID 38225249, 2024). "Like SPON2, preclinical studies implicate myocardial THBS2 expression in protection from myocardial fibrosis and dysfunction with aging or in response to hypertension." (PMID 38225249, 2024).
non-small cell lung carcinoma (1 paper, 2022). A group of at least three distinct histological types of lung cancer, including non-small cell squamous cell carcinoma, adenocarcinoma, and large cell carcinoma. "Rescue experiments were carried out to confirm the role of HOTAIRM1/miR-328-5p/SPON2 pathway in promoting the migration and invasion of non-small cell lung cancer." (PMID 36153414, 2022). "SPON2 is one of the extracellular matrix proteins, which is closely related to the progression of a variety of tumors including non-small cell lung cancer (NSCLC), but its upstream regulation mechanism remains unclear." (PMID 36153414, 2022).
oral cancer (1 paper, 2015). "SPON2 mRNA was also significantly increased in high metastatic oral cancer cell line comparing with the parental cell line." (PMID 25945835, 2015).
PFAPA syndrome (1 paper, 2025). An auto inflammatory syndrome characterized by recurrent febrile episodes associated with aphthous stomatitis, pharyngitis and cervical adenitis. "Epigenetic changes such as differences in methylation of Phosphoinositide-3-Kinase Adaptor Protein 1 (PIK3AP1) and spondin 2 (SPON2) gene could also be associated with the pathogenesis of PFAPA syndrome." (PMID 40310068, 2025).
rectal adenocarcinoma (1 paper, 2015). "We found that SPON2 expression was significantly upregulated in rectal adenocarcinoma tissues comparing with paired normal colonic rectum tissues using Gaedcke Colorectal dataset tissues (n = 65, p = 4.3E-20, paired Student's t test)." (PMID 25945835, 2015).
stomach adenocarcinoma (1 paper, 2023). "About stomach adenocarcinoma, we found a correlation between high expression of SPON2 and poor OS prognosis (P = .23) and poor DFS (P = .076)." (PMID 37713832, 2023).
type-2 diabetes (1 paper, 2017). "SPON2 also plays an important role in some noncancerous diseases, such as type-2 diabetes and chronic kidney injury disease." (PMID 28938639, 2017).
tumor (45 papers, 2010 to 2026). "Specifically, SPON2 was enriched in tumor-associated epithelial clusters, while MSMB was detected in secretory/luminal epithelial subsets." (PMID 41200187, 2025). "Our research aims to find the specific regulatory pathway of SPON2 by exploring the potential crosstalk between tumor cells and cancer-associated fibroblasts (CAFs) in tumor microenvironment (TME) of NSCLC." (PMID 36153414, 2022). "Univariate analysis indicated that tumor grade, sarcomatoid, SPON2 protein, and SPON2 mRNA (all P < 0.05) were significantly associated with RFS." (PMID 32952742, 2020). "In conclusion, this study indicated that SPON2 was overexpressed in ccRCC and associated with tumor stage, Fuhrman grade, and recurrence after surgery in patients with localized ccRCC." (PMID 32952742, 2020). "In several investigations, it has been shown that the abnormal expression of spondin-2 in cancer cells is associated with tumor progression." (PMID 28060752, 2017). "Additionally, the mRNA expression of SPON2, a member of the extracellular matrix protein family used as a broad-spectrum tumor marker and implicated in the regulation of tumor metastasis and progression, was significantly altered by infection (24.99-fold)." (PMID 40906080, 2025). "Notably, SPON2 expression was enriched in tumor-associated epithelial clusters, while MSMB expression was detected in secretory/luminal epithelial cell subsets." (PMID 41200187, 2025). "High SPON2 expression is associated with tumor progression related pathways." (PMID 37713832, 2023). "Sapiens spondin-2 (SPON2) is a protein found in the extracellular matrix that plays a role in a number of processes, including immune reactions and cell adhesion, and is closely linked to the emergence of a number of tumor types." (PMID 37713832, 2023). "Blocking M2 polarization or depleting macrophages suppresses SPON2-induced tumor growth and invasion, while inhibition of the SPON2/integrin β1/PYK2 axis reduces transendothelial monocyte migration and TAM-mediated cancer progression." (PMID 41438574, 2026). "Functional research shows that SPON2 promotes tumor cell proliferation, migration, and invasion, while silencing of SPON2 suppresses tumor growth in vitro and in vivo." (PMID 41200187, 2025). "In vivo, SPON2 knockdown in OS xenografts suppresses tumor growth, lung metastasis, and M2 polarization, while increasing M1-associated markers." (PMID 40730813, 2025). "The partial restoration of tumor-promoting features by LPS in SPON2-knockdown models supports the involvement of NF-κB/VEGF signaling in SPON2-related effects." (PMID 40730813, 2025). "Our study reveals a previously unrecognized role of SPON2 in shaping the tumor immune microenvironment by promoting macrophage polarization in OS." (PMID 40730813, 2025). "In this study, we identify SPON2 as a key modulator of OS progression, highlighting its role in enhancing tumor cell proliferation, facilitating metastasis, promoting EMT, and modulating macrophage polarization." (PMID 40730813, 2025). "This aligns with prior reports in other malignancies, where SPON2 has been shown to promote cytokine production and support tumor-promoting immune responses." (PMID 40730813, 2025). "Western blot analysis of tumor tissues from nude mice showed that SPON2 knockdown significantly increased E-cadherin levels while reducing the expression of N-cadherin, Vimentin, NF-κB p65, and VEGF, indicating a suppression of EMT." (PMID 40730813, 2025). "Since EMT is a key step in tumor metastasis, these results suggest that SPON2 enhances OS cell plasticity and invasiveness through EMT induction." (PMID 40730813, 2025). "Normality of ΔΔCt values was assessed using the Shapiro–Wilk test (p > 0.05 for both genes); paired two-tailed t-tests were then applied to compare tumor versus matched normal tissues, yielding p = 0.003 for SPON2 and p = 0.02 for MSMB." (PMID 41200187, 2025).
tumor (continued). "In summary, our study identifies SPON2 as a key contributor to OS progression by facilitating tumor cell proliferation, EMT, angiogenesis, and M2 macrophage polarization through the NF-κB/VEGF signaling axis." (PMID 40730813, 2025). "This interpretation is supported by induction of host stress- and remodeling-related genes (Ddit3, Gstp1, Spon2), representing a molecular signature of tissue repair and immune infiltration consistent with the observed tumor regression." (PMID 41463401, 2025). "SPON2 exhibited strong overexpression in tumor tissues compared to matched normals, with a mean ΔΔCt of –4.2, corresponding to an approximately 18-fold increase in expression(mean fold-change = 18.2 ± 2.4, mean ± SD)." (PMID 41200187, 2025). "Given SPON2’s dual role in promoting both tumor progression and immune modulation, it presents a compelling target for therapeutic intervention." (PMID 40730813, 2025). "Further work is needed to understand how endogenous inflammatory factors interact with SPON2-regulated pathways in shaping tumor progression." (PMID 40730813, 2025). "We further delineate the involvement of the NF-κB/VEGF signaling pathway in SPON2-mediated regulation of tumor invasion and angiogenesis." (PMID 40730813, 2025). "Although SPON2 has been reported to promote tumor proliferation and angiogenesis in various cancers, its role in OS remains unexplored." (PMID 40730813, 2025). "SPON2 secreted by tumour cells promotes transendothelial migration of plasma-derived monocytes by activating the Pyk2 signalling pathway." (PMID 40045379, 2025). "Spondin 2 (SPON2), a matricellular protein 2, is essential for recruiting lymphocytes and initiating immune responses, as well as having a role in tumor progression." (PMID 38542388, 2024). "Significantly, DDP treatment caused a significant reduction in Spon2 levels in both A549/DDP cells and tumor tissues from A549/DDP xenograft mice, compared to the A549/DDP group; meanwhile, IGF2BP2 deficiency further reduced Spon2 expression." (PMID 39731162, 2024). "Tumor cell-derived spondin 2, an ECM glycoprotein, plays a complex role in macrophage and neutrophil recruitment during inflammation." (PMID 39068459, 2024). "The extracellular matrix glycoprotein, spondin 2 (SPON2), derived from tumor cells, can inhibit tumor growth and invasion by indirectly inducing M1 poles." (PMID 39100676, 2024). "We found that LIHC and TGCT had increased expression in tumor tissues, whereas SPON2 had decreased expression in the LUAD, BRCA, OV, and THCA tumor tissues compared to normal tissues." (PMID 37713832, 2023). "To investigate the relationship between SPON2 expression and the prognosis of patients with various cancers, we classified tumor cases into 2 groups based on the degree of SPON2 expression: a high-expression group and a low-expression group." (PMID 37713832, 2023). "The expression of SPON2 is significantly correlated with the infiltration of immune cells into the tumor microenvironment and the immunotherapy response of various cancers." (PMID 37713832, 2023). "To determine the features of SPON2 mRNA expression, we combined tumor and normal samples from TCGA datasets." (PMID 37713832, 2023). "In our study, SPON2 was overexpressed in the majority of tumor tissues as compared to normal tissues." (PMID 37713832, 2023). "While high expression of SPON2 has been linked to poor prognosis in HCC patients, it has also been found to inhibit tumor metastasis by promoting the infiltration of M1-like macrophages." (PMID 37287981, 2023). "Inhibition of SPON2 in CAFs reduced the aggressiveness of co-cultured tumor cells compared with the NC group." (PMID 36153414, 2022). "It was shown that SPON2 in this case promotes M1-like macrophage recruitment and inhibits tumor metastasis." (PMID 35585513, 2022).
tumor (continued). "Then, qPCR was performed to verify the total RNAs extracted from ten pairs of clinical samples resected during surgery, and the results showed that the expression of SPON2 in tumor tissues was significantly higher than that of the adjacent normal tissues." (PMID 36153414, 2022). "ECM secretion by cancer cells in low-adhesion environments has been suggested previously; for example, increased expression of SPARC, MPG and SPON2 has been reported in circulating tumour cells from patients." (PMID 36546396, 2022). "The results showed that SPON2 protein was mainly localized in the cytoplasm of tumor cells and areas of ECM." (PMID 34583750, 2021). "The data showed that knockdown of SPON2 decreased the liver metastasis of orthotopic tumor and macrophages infiltration." (PMID 34583750, 2021). "In the current study, we demonstrated the critical roles of the tumor-derived SPON2 in the infiltration of M2-TAMs and tumor progression in advanced CRC." (PMID 34583750, 2021). "Our findings demonstrate that SPON2-driven M2-TAM infiltration plays an important role during CRC tumor growth and metastasis." (PMID 34583750, 2021). "Subcutaneous injection of MC38 cells showed that knockdown of SPON2 inhibited tumor growth, the infiltration of M2-TAMs and tumor invasion." (PMID 34583750, 2021). "We also show that SPON2-driven M2-TAM infiltration plays an important role in tumor invasion and metastasis in CRC." (PMID 34583750, 2021). "Taken together, these data suggest that the function of SPON2 in promoting tumor progression mainly depends on macrophages in CRC." (PMID 34583750, 2021). "In the current study, we demonstrated that tumor cell-derived SPON2 promotes the infiltration of TAMs with an M2-like phenotype and tumor metastasis in CRC." (PMID 34583750, 2021). "At the immune system level, it promotes infiltration of M1-like macrophages and inhibits tumor metastasis by activating the SPON2-α5β1 integrin signaling that in turn inactivates RhoA and prevents F-actin assembly." (PMID 34445986, 2021). "IHC analysis of subcutaneous tumours generated by SPON2‐knockout SGC‐7901 cells revealed that compared with the controls, the levels of CDH1 expression increased, those of CDH2, VIM and p‐ERK1/2 decreased, and those of ERK1/2 were unchanged." (PMID 31691494, 2020). "The C indices were 0.771, 0.706, and 0.915, respectively, when RFS was assessed with tumor grade, sarcomatoid, and SPON2 mRNA alone." (PMID 32952742, 2020). "For the subgroups of smaller tumor size and T3/T4 patients, significant correlations were found between Spondin-2 status and OS (P < 0.001 and P = 0.001, respectively) and RFS (P < 0.001 and P = 0.002, respectively)." (PMID 28060752, 2017). "An interesting finding would be that the plasma SPON2 of the CRC patients (average = 21.6 ng/mL) was downregulated after surgery (average = 12.7 ng/mL), suggesting that SPON2 was closely associated with tumor burden." (PMID 25945835, 2015). "Renate Parry's research suggested that SPON2 mRNA is expressed predominantly in the prostate (both tumor and normal samples), and at significantly lower levels in other tissues." (PMID 22615945, 2012). "Aberrant DNA methylation of two genes, AOX1 and SPON2, were confirmed via bisulfate sequencing, with most of the respective CpG sites showing significant differences between tumor samples and normal tissues." (PMID 23119026, 2012). "Taken together, these findings suggested that SPON2 may promote tumor invasion and metastasis by activating the p38 MAPK pathway, anti-apoptotic signaling, angiogenesis pathway, RANK/RANKL signaling, and extracellular matrix degradation pathway." (PMID 40730813, 2025). "To further investigate the mechanism by which SPON2 influences macrophage behavior and tumor progression in vivo, we examined whether it affects EMT through NF-κB/VEGF signaling axis." (PMID 40730813, 2025).
tumor (continued). "Mice injected with SPON2-knockdown cells developed fewer lung metastases, exhibited reduced metastatic lesions by haematoxylin and eosin (H&E) staining, and showed lower tumor and lung weights compared to the control and sh-NC groups." (PMID 40730813, 2025). "In addition, SPON2 secreted by tumour cells further exacerbates the immunosuppressive state by activating the Pyk2 signalling pathway and promoting macrophage differentiation towards M2-TAMs." (PMID 40045379, 2025). "However, in hepatocellular carcinoma, SPON2 promotes the infiltration of M1-like macrophages while inhibiting tumor cell migration and metastasis, highlighting differential impacts based on cancer type and TME." (PMID 39068459, 2024). "Furthermore, MeRIP-seq data showed that IGF2BP2 downregulation remarkably elevated m6A levels of spondin 2 (Spon2) and reduced mRNA levels of Spon2 in tumor tissues from A549 tumor-bearing mice." (PMID 39731162, 2024). "Also, by examining the SPON2 gene’s survival and prognosis, we have drawn various findings for various tumor types." (PMID 37713832, 2023). "We looked examined SPON2’s genetic status in several tumor samples from the TCGA cohorts." (PMID 37713832, 2023). "The expression of Sapiens spondin-2 in most tumor tissues was higher than that of normal tissues." (PMID 37713832, 2023). "Remarkably, several of these target genes were down-regulated following miR-Combo treatment, and have been shown to be involved in GBM progression (RAP2A), angiogenesis (SPON2), migration (CXCR4), and are associated with an increase in tumor grade (IGF2BP3, SERPINH1)." (PMID 37749143, 2023). "The discrepancy of SPON2 expression on tumor behavior could indicate that SPON2 could affect different tumor types in a different ways." (PMID 35585513, 2022). "These synergistic changes supported that SPON2 in CAFs could be regulated by HOTAIRM1 from tumor cell exosomes." (PMID 36153414, 2022). "This also inspired us that tumor cells may regulate SPON2 expression in CAFs through exosome pathway, so as to promote the migration and invasion of tumor cells." (PMID 36153414, 2022). "Moreover, overexpression of SPON2 in tumor cells significantly increased, while knockdown of SPON2 in tumor cells decreased the migration of THP-1 cells and the numbers of THP-1 cells adhered to the HUVECs." (PMID 34583750, 2021). "Moreover, SPON2-driven M2-TAMs infiltration plays an important role during CRC tumor growth and metastasis." (PMID 34583750, 2021). "Moreover, the expression of macrophages markers (CD68 and MAC2) and M2-like macrophages markers (CD206) significantly increased in THP-1 cells co-cultured with SPON2-overexpressing CRC tumor cells compared with the control tumor cells." (PMID 34583750, 2021). "Furthermore, overexpression of SPON2 in tumor cells obviously increased, while knockdown of SPON2 in tumor cells dramatically decreased the transendothelial movement." (PMID 34583750, 2021). "SPON2 expression was found to be significant in tissues with advanced stage of tumor invasion." (PMID 32492954, 2020). "The high expression of SPON2 in tumour tissues is related to the activation of its promoter region." (PMID 31691494, 2020). "Spondin-2 inhibits EC migration and tube formation and its over-expression impairs angiogenesis and tumor growth, suggesting that it may function as a potential target for anti-angiogenic therapy as well as a biomarker for CRC." (PMID 32456248, 2020). "Spondin-2 is upregulated in GC and it may regulate angiogenesis also in this tumor context, representing a possible biomarker and/or new therapeutic target for GC." (PMID 32456248, 2020). "Interestingly, C indices of tumor grade and sarcomatoid were improved to 0.893 and 0.915 with supplement of SPON2 mRNA." (PMID 32952742, 2020). "Therefore, the relationship of SPON2 and immune-related genes within tumor microenvironment in various cancer is further required to be studied." (PMID 32492954, 2020).